RNU6ATAC6P (RNA, U6atac small nuclear 6, pseudogene)
Gene: Small nuclear RNA gene on chromosome 3 (87,910,220 to 87,910,345, forward strand). Ensembl gene ENSG00000221059.
Homologues: Orthologues: chimpanzee RNU6ATAC6P (100% identical), macaque RNU6ATAC6P (96% identical). Paralogues in human: RNU6ATAC (90% identical), RNU6ATAC21P (83% identical), RNU6ATAC7P (81% identical), RNU6ATAC41P (80% identical), RNU6ATAC27P (79% identical), RNU6ATAC8P (78% identical), RNU6ATAC19P (66% identical), RNU6ATAC39P (55% identical), RNU6ATAC22P (52% identical).